ATM (ATM serine/threonine kinase)
Diseases named in the same sentence as ATM in open-access papers (continued):
Sharing a sentence is not in itself a finding about the gene and the disease.
ovarian carcinoma (continued). "We have further shown that ATM inhibitors can re-sensitise immortalised platinum-resistant ovarian cancer cells, suggesting that ATM inhibition may be an additional novel candidate combination chemotherapy approach." (PMID 35778553, 2022). "More recent studies have improved our understanding of inherited ovarian cancer risk beyond BRCA-related HBOC, and have allowed more detailed estimates of ovarian cancer risk for several homologous recombination (HR)-related genes with moderate-penetrance such as BRIP1, RAD51C/D, PALB2, and ATM." (PMID 35163487, 2022). "The common germline mutations in ovarian cancer includes BRCA1, BRCA2, ATM, MSH3 and PALB257." (PMID 33432021, 2021). "Screening for pancreatic and ovarian cancers in carriers of ATM pathogenic variants is not recommended in the absence of familial antecedents, while men should be encouraged to participate in prostate cancer screening." (PMID 32733558, 2020). "Considering the key role of ATM (ataxia telangiectasia mutated kinase) in DSB repair, we hypothesized that HMGA2 could regulate ATM to influence the sensitivity to PARPi in ovarian cancer cell." (PMID 32005272, 2020). "Olaparib has been shown to sensitize cells to these treatments in cells that have deficiencies in some DNA repair mechanisms and, for this reason, it has been used in breast and ovarian cancer with BRCA1 mutations, or in mantle cell lymphomas with alterations of the ATM pathway." (PMID 31101118, 2019). "The pathogenic variants in BC-related genes (2 in ATM and 1 in BRCA2) were found in 3 women with BC or ovarian cancer, while the MSH6 and the heterozygous MUTYH p.Gly393Asp pathogenic variant was found in a woman with endometrial cancer at 57 years and BC diagnosis at 56 years, respectively." (PMID 29371908, 2018). "Taken together, our study suggest that Wip1 blocks cellular metastasis of serous ovarian cancer through the ATM/Akt/snail mediated signaling, which may be used to improve the efficiency of ovarian cancer treatment." (PMID 27121065, 2016). "Inhibitors of DNA repair enzymes including APE1, ATM, ATR, DNA-PK and PARP have been developed and the PARP inhibitor olaparib is the first-in-class approved in Europe and the USA for the treatment of advanced BRCA-mutated ovarian cancer." (PMID 26097887, 2015). "Given the complex network and the critical role in DDR we hypothesized and have provided evidence here that ATR, ATM and DNA-PKcs expressions have prognostic and predictive significances in ovarian cancer patients." (PMID 26674120, 2014). "Investigating ATM/DNA-PKcs/ATR protein together we found that tumours that have high ATM/DNA-PKcs/ATR protein expression have poor ovarian cancer specific survival (p = 0.000252) and progression free survival (p = 0.001) compared to tumours that are low ATM/DNA-PKcs/ATR protein expressers." (PMID 26674120, 2014). "However, the role of DGAT1 in ovarian cancer during ATM inhibition remains poorly understood." (PMID 40554491, 2025). "In Japan, the proportion of germline variants in ovarian cancer is approximately 18%, and the major genes are BRCA1, BRCA2, mismatch repair genes [MutL protein homolog (MLH) 1, MLH2, MLH6, and postmeiotic segregation increased 2], RAD51 Paralog D, and ataxia telangiectasia mutated (ATM)." (PMID 39807103, 2025).
ovarian carcinoma (continued). "In a study assessing the function of multiple ATM variants of unknown significance, ATM Ser49Cys exhibited reduction in homology-directed repair with non-significant defects in ATM phosphorylation targets in ovarian cancer." (PMID 38338943, 2024). "However, the ATM inhibition’s influence in ovarian cancer treatment remained unclear." (PMID 35795059, 2022). "Therefore, differential ATM expression level/activity between osteosarcoma and ovarian cancer cells could explain the differences seen in our results." (PMID 36233063, 2022). "In addition, it is well known that some HRR genes such as BRCA1/2, ATM, BRAD1, BRIP1, PALB2, RAD51C, and RAD51D are associated with high risk of ovarian cancers, and tissue detection might be a good way to learn the germline status." (PMID 35186721, 2022). "Thus, Wip1 may suppress ovarian cancer metastasis through negative regulation of p-ATM, p-Akt, and Snail, which was also evidenced in the limited clinical specimens." (PMID 27121065, 2016). "However, for ATM (and moderate-penetrance genes in general), specific association are less definite, as large studies often do not differentiate between epithelial ovarian cancer types, while information on specific subtypes is mainly based on isolated reports." (PMID 39984762, 2025). "The expression of PRDX1, ATM, and MRE11 were investigated using Tissue MicroArrays (TMA) of 331 consecutive ovarian epithelial cancer cases treated at Nottingham University Hospitals (NUH) between 1997 and 2010." (PMID 40387816, 2025). "MIL induces DNA damage through topoisomerase II inhibition, activating the NF-κB pathway in a pro-apoptotic role; it enhances ATM/IKK/NF-κB signaling, leading to apoptosis even in drug-resistant ovarian cancer models." (PMID 39949780, 2025). "ATR/ATM kinases, key molecules in DDR, are potential therapeutic targets for overcoming drug resistance in ovarian cancer." (PMID 38539161, 2024). "A recent study demonstrated that the loss of RBM39 induces splicing defects in key DNA damage repair genes, such as ATM and BRCA1, in ovarian cancer, leading to increased sensitivity to cisplatin and various PARPi18." (PMID 38789724, 2024). "The NBDep method also identified 43 missense driver genes in ovarian cancer having a significant protein–protein network (p-value = 2.12e−06) where well-known genes such as RHOA, PIK3CA, and ATM are among these genes." (PMID 38195844, 2024). "Our custom gene panel resulted in newly identified P/LP findings for 21% of the tested population, with 13% of P/LP findings specific to ovarian cancer (including BRCA1/2 and ATM)." (PMID 39061202, 2024). "On the other hand, ATM and PALB2 are considered moderate penetrance genes in breast and ovarian cancer, and MSH6, PMS2, and EPCAM are considered moderate penetrance genes in LS CRC." (PMID 38201484, 2023). "Next, we examined the changes of BRCA1, BRCA2, ATM, and RAD51, key genes of HR repair pathway, in MEnZn‐CuO NPs‐treated ovarian cancer cells." (PMID 37206208, 2023).
ovarian carcinoma (continued). "Our results advanced the current understanding by showing that downregulating of PKM2 affected the expression of the HR-related proteins ATM, γH2AX and BRCA1 in ovarian cancer cells." (PMID 35280680, 2022). "Here, we report that administration of the ATM inhibitor KU60019 led to impaired migration and enhanced apoptosis in the ovarian cancer cell line SKOV3, accompanied by abnormally elevated O-GlcNAc transferase and O-GlcNAcase expression levels." (PMID 35795059, 2022). "Other HRR pathway-related genes (ATM, ATR, CDK12, FANCA, FANCD2 and RAD50) were also found to play an essential role in ovarian cancer pathogenesis." (PMID 36729997, 2022). "However, in the current study, we did not observe selective toxicity for FEN1 inhibitor in ATM-deficient HeLa cells or MRE11 deficient ovarian cancer cells implying that this phenomenon could be cell line dependent." (PMID 33919707, 2021). "Induction of ATM phosphorylation and PARP-1 by the antagonists was shown in the ovarian cancer cells." (PMID 29184090, 2017). "Our data supports a rational approach using small molecule inhibitors of ATM, DNA-PKcs and ATR, currently under pharmaceutical development, for ovarian cancer therapy." (PMID 26674120, 2014). "In conclusion, we have provided evidence that ATM, DNA-PKcs and ATR are promising prognostic and predictive biomarkers in ovarian cancer." (PMID 26674120, 2014). "In the current study we have provided evidence that ATM, DNA-PKcs and ATR are promising biomarkers in ovarian cancer." (PMID 26674120, 2014). "The data presented here provides evidence that ATM, ATR and DNA-PKcs involved in DDR are not only promising biomarkers but are also rational targets for personalized therapy in ovarian cancer." (PMID 26674120, 2014). "Together the data support the hypothesis that PRDX1 interaction with ATM and the MRN components could influence patients’ prognosis in ovarian cancers." (PMID 40387816, 2025). "Unlike BRCA1/2, PVs in ATM and CHEK2 do not confer sufficient ovarian cancer risk to warrant recommendation of risk-reducing salpingo-oophorectomy." (PMID 40298171, 2025). "Many clinical trials, including trials evaluating drugs targeting ATR, ATM, WEE1, checkpoint kinase 1/2 (CHK1/2), BRCA1/2 and RAD51, have been designed to evaluate interference with DDR pathways to overcome platinum and PARPi resistance in ovarian cancer." (PMID 38539161, 2024). "Although the relationship of ATM and PALB2 genes with ovarian cancer risk was not clear, RRSO was also performed in two patients considering personal and family histories." (PMID 37386498, 2023). "We, however, conclude that targeting ATM in SKOV3 is a potential important strategy in disrupting ovarian cancer proliferation, and overexpressing RYBP may offer new avenues for inhibiting ATM activity." (PMID 36233063, 2022). "The real-world clinical impact of positive findings in ATM, CHEK2, PALB2, and other DDR genes conferring an increased risk of breast and/or ovarian cancer have not been well studied." (PMID 35626031, 2022). "Mutations in non-BRCA HR genes, including ATM, CHEK2, PALB2 and RAD51c, have been reported to be predictors of survival in ovarian cancer patients." (PMID 35740616, 2022). "Notably, in patients with ovarian cancer, a significant number of PVs were identified in the moderate penetrance RAD51 genes; RAD51C (1.5%) and RAD51D (1%), followed by the MMR and ATM genes." (PMID 34326862, 2021). "Furthermore, combination therapy with 673A and the DSB repair pathway inhibitors, AZD1390 (ATM) and AZD6738 (ATR), resulted in a synergistic killing ovarian cancer cell lines." (PMID 33664846, 2021).
ovarian carcinoma (continued). "In addition, ATM regulates PTEN, the antagonist of PI3K through p85α and XIAP mediated proteasome degradation in ovarian cancer cells (OVCAR3, OVCAR4) and human epithelial ovarian tumors." (PMID 33802884, 2021). "It was observed that as opposed to the NIH-OVCAR3 cells, ATM was more likely to be amplified or show higher mRNA expression in ovarian cancers (8%) compared to 2% with deep deletions (or low mRNA levels)." (PMID 32709004, 2020). "We also observed pathogenic mutations in several genes that have not traditionally been associated with increased risk of ovarian cancer (PALB2, ATM, and CHEK2)." (PMID 28281021, 2017). "In clear contrast, dual ATM/ATR inhibition strongly potentiates the activity of both ETs against human cervical and ovarian carcinoma cells by efficiently blocking the formation of γ-H2AX, MDC1, BRCA1 and Rad51 foci following ET-exposure thereby resulting in extensive chromosome damage." (PMID 27029031, 2016). "MIL increased the level of p-ATM and p-IKK protein in both human ovarian cancer cells." (PMID 27447570, 2016). "We here report the retrospective analysis of 7 polymorphisms in 5 genes involved in the cellular response to cisplatin (DDP): ATM, ATR, Chk1, Chk2 and CDK12 in a cohort of 240 cancer patients with stage III/IV ovarian cancer underwent surgery and adjuvant chemotherapy." (PMID 27905519, 2016). "High ATM protein (p = 0.001), high ATM mRNA (p = 0.018), high DNA-PKcs protein (p = 0.002), high DNA-PKcs mRNA (p = 0.044) and high ATR protein (p = 0.001) expressions are correlated with poor ovarian cancer specific survival (OCSS)." (PMID 26674120, 2014). "ATM, ATR and DNA-PKcs expressions may have prognostic and predictive significances in epithelial ovarian cancer." (PMID 26674120, 2014). "Our objective was to evaluate if ATM, ATR and DNA-PKcs expressions could predict response to therapy and clinical outcome in epithelial ovarian cancers." (PMID 26674120, 2014). "Analyses of expression of phosphorylated Chk1, phosphorylated Chk2 and autophosphorylated forms for ATM, DNA-PKcs and ATR may provide further insights into the clinicopathological significance of the DNA damage signalling pathways in ovarian cancers." (PMID 26674120, 2014). "Taken together, our data suggests that XRCC1 based personalization using ATM, DNA-PKcs or ATR inhibitors may be feasible and this approach clearly warrants further investigation in vivo in sporadic epithelial ovarian cancers." (PMID 26674120, 2014). "Altered expression of ATM, DNA-PKcs and ATR may have prognostic and predictive significances in ovarian cancer." (PMID 26674120, 2014). "Owing to its functional overlap with ATM, a DDR kinase already implicated in BC susceptibility, ATR has been previously tested as a potential candidate gene in two breast and ovarian cancer cohorts of respectively 126 and 54 patients without alterations of BRCA1/2." (PMID 36749285, 2023). "Here, we found that ATM inhibition could elevate the expression of OGT and OGA while significantly suppressing the level of miR-542-5p in ovarian cancer SKOV3 cells When miR-542-5p was overexpressed under ATM inhibition, OGT expression was effectively inhibited." (PMID 35795059, 2022).
ovarian carcinoma (continued). "Whilst small molecule inhibitors of ATM and ATR are under clinical trial evaluation, Mre11 blockade could impair both ATM and ATR mediated pathways simultaneously and could be an effective strategy in ovarian cancers which frequently manifest genomic instability and replication stress." (PMID 35853939, 2022). "An additional 3 breast and ovarian cancer cases were not analyzed in this cohort because in additional to RAD51B germline mutations, they carried another high or moderate penetrance mutation in a cancer susceptibility gene (1 each BRCA2, RAD51D, ATM)." (PMID 34635660, 2021). "Importantly, both ALDH knockout and 673A treatment of ovarian cancer cell lines synergized with DNA damage checkpoint inhibitors, AZD1390 (ATM inhibitor) and AZD6738 (ATR inhibitor), resulting in a synergistic decrease in cell viability in vitro and tumor growth in vivo." (PMID 33664846, 2021). "Previous work suggested a similarly modest increase in risk for ATM and PALB2, but not for MRE11A13,14, casting doubt on whether the latter is truly an ovarian carcinoma predisposition gene." (PMID 32242007, 2020). "However, this study utilized a panel consisting of BRCA1/2, PALB2, CHEK2, and ATM only, whereas the GRACE panel was more extensive and included genes not traditionally associated with ovarian cancer, which explains our higher prevalence of P/LP variants overall." (PMID 39061202, 2024). "Because baicalein significantly activates the ATM/CHK2/CDC25C signaling axis, which may lead to G2/M arrest, we next determined whether blocking CHK2 could attenuate baicalein-induced G2/M arrest to confirm the role of CHK2 activation in baicalein-mediated G2/M arrest in ovarian cancer cells." (PMID 36770705, 2023). "The analysis of the mRNA and protein levels of the ATM and MEN1 showed no change in the expression level in patients with ovarian cancer compared with the control group." (PMID 35807169, 2022). "Our results showed that ADAR1 knockdown caused increase of phosphorylation of Chk1 and ATR, but not phosphorylation of Chk2 and ATM, indicating that single strand DNA was generated by ADAR1 knockdown in ovarian cancer cells." (PMID 35711824, 2022). "Similarly, in relapsed platinum-sensitive high-grade ovarian cancer patients, therapeutic responses to Rucaparib were not restricted to BRCA-mutated tumors, and were observed in several patients with mutations to other HR genes including ATM, NBN, RAD51C, and RAD51D." (PMID 35205643, 2022).